CXCR2 (C-X-C motif chemokine receptor 2)
Diseases named in the same sentence as CXCR2 in open-access papers (continued):
Sharing a sentence is not in itself a finding about the gene and the disease.
tumor (continued). "To confirm the inhibition of tumor growth associated with decreased chemokine expression in Ccn1‐KO tumor, we focused on CXC chemokines, including CXCL1, CXCL3, and CXCL5, which bind to CXCR2, as well as CCL2 and CCL7, which bind to CCR2." (PMID 40287974, 2025). "The binding of CXCL1 and CXCR2 can be influenced by the NF-κB pathway, impacting the proliferation and spread of tumor cells." (PMID 40841364, 2025). "In summary, targeting the CXCL1–CXCR2 axis holds significant promise for future cancer therapies, and focusing on CXCR2 allows for a more comprehensive disruption of tumor-promoting signaling pathways, as well as direct translational applicability." (PMID 40490643, 2025). "Inhibiting CXCR2 disrupts the recruitment of these cells to the tumor site, thereby reducing their immunosuppressive effects." (PMID 40109854, 2025). "Immunohistochemical analysis of the TA muscle showed that CXCR2 expression was upregulated in tumor bearing mice and downregulated by CXCL5 neutralization." (PMID 41392310, 2025). "In a corresponding mouse tumour model established with RM-1/CXCR2 cells, tumour tissues were harvested for analysis after tumour development." (PMID 41163221, 2025). "In the premetastatic lung microenvironment, neutrophils are recruited by HSP70, a soluble mediator secreted by tumor cells that induces CXCR2-dependent chemokines and promotes the progression of lung metastasis." (PMID 41214328, 2025). "Sarcosine competitively inhibits the GlyT1 transporter of dendritic cells (DCs), thereby upregulating the expression of COX-1 and CXCR2, and promoting DCs’ migration to the tumor area." (PMID 40406272, 2025). "Chemokines entered the bloodstream, which interacted with CXCR-1 and CXCR-2 (G protein-coupled receptors) on neutrophils and facilitated their directed movement toward tumor sites." (PMID 40697377, 2025). "Epi0_AGR2 demonstrated a specific interaction with neutrophils via the CXCL signaling pathway, and the interactions mediated by CXCR2 between tumor cells and neutrophils were found to be substantially enriched in the metastatic group." (PMID 40657372, 2025). "Nevertheless, interleukin-8, also known as CXCL8, binds to the receptors CXCR1 and CXCR2 has been shown to mediate tumour progression, epithelial-mesenchymal transition, invasion, and angiogenesis." (PMID 40852716, 2025). "Snail-expressing tumor cells increase the secretion of CXCL2 which is the ligand of CXCR2, promoting the recruitment of neutrophils." (PMID 41254689, 2025). "Our findings, consistent with previous reports, demonstrate that SB225002, a selective CXCR2 antagonist, exerts potent anti-tumor activity in NB cell lines and 3D spheroid models, which more closely recapitulate in vivo tumor physiology." (PMID 41155662, 2025). "Further analysis revealed a positive correlation between CXCL8 expression in pMQs and its receptors, CXCR1 and CXCR2, in matched tumor cells." (PMID 39937005, 2025). "MDSC accumulation occurs within the GBM microenvironment through the interaction of tumor-derived chemokines (CXCL1/2/3) with their receptor CXCR2." (PMID 40948940, 2025). "The ability of TAMs to engulf tumour cells also decreased after activation of the IL-8/CXCR2 pathway." (PMID 41163221, 2025). "Promisingly, A2AR inhibition by the small molecule CPI-444 and CXCR2 inhibition by the small molecule SB225002 abrogated tumor growth and NET area in murine xenografts; CPI-444 treatment suppressed CXCL5 expression." (PMID 40507214, 2025). "Metabolomic profiling of RM-1/CXCR2 tumours revealed elevated palmitic acid and ω−3/ω−6 very-long-chain polyunsaturated fatty acids (VLC-PUFAs) in the TME, and TAMs exhibited significantly greater lipid uptake than did spleen-derived macrophages." (PMID 41163221, 2025). "By targeting the CXCR2 signaling axis, these inhibitors aim to restore anti-tumor immunity and overcome resistance to existing therapies." (PMID 41254689, 2025).
tumor (continued). "Gastric cancer metastases are driven by interactions dominated by CXCR2 between tumor cells and macrophages." (PMID 41155662, 2025). "The prominent neutrophil receptor, CXCR2, is responsible for the infiltration of neutrophils into tumour milieu, which regulates the involvement of neutrophils in tumourigenesis, angiogenesis and immune suppression." (PMID 40852716, 2025). "The interaction between MIF and its receptor CXCR2 on MDSCs induces the migration of MDSCs toward the tumor sites." (PMID 41159021, 2025). "Our findings further demonstrate that IL-8 signalling through CXCR2 upregulates CD47 expression in tumour cells, potentially influencing macrophage behaviour within the TME." (PMID 41163221, 2025). "Research has shown that CXCR2 signaling is critical in cancer biology, influencing tumor growth and metastasis by modulating the tumor microenvironment." (PMID 41259376, 2025). "Anwulignan exerts unique effects by modulating the PPARα/CXCR2 signaling pathway in the spinal dorsal horn, reducing the tumor burden and increasing osteoblast activity." (PMID 40079428, 2025). "Glutamic acid-leucine-arginine positive (ELR+) CXC chemokines and their receptors, CXC chemokine receptor 1 and 2 (CXCR1 and CXCR2), mediate both inflammatory responses and tumor progression." (PMID 41425704, 2025). "The CXCL8/CXCR2 axis plays a significant role in tumor microenvironment (TME) remodeling, cancer plasticity, and the development of resistance to both chemotherapy and immunotherapy." (PMID 40006729, 2025). "In cirrhosis and HCC, chemokines including IL-8 and CXCL family members, together with their receptors CXCR1 and CXCR2, orchestrate marrow egress, circulation, and tumor homing." (PMID 41488615, 2025). "At the same time, CXCR2 activation on such lymphocytes caused an increase in interferon-γ (IFN-γ) secretion, a cytokine that enhances the anti-tumor immune response." (PMID 40427171, 2025). "This indicated that the expression of ALDH1A1 is crucial for IL-8 to promote ICC progression, and inhibiting IL-8/CXCR2 can also inhibit the tumor-promoting effect of ALDH1A1." (PMID 40008905, 2025). "Recent studies emphasize the wide-spectrum anti-tumor potential of SB225002 in multiple cancers by targeting CXCR2." (PMID 41155662, 2025). "Concurrently, TME, characterized by hypoxia and oxidative stress, induces the expression of CXCR2 on tumor cells." (PMID 40497988, 2025). "When neutrophils are reduced or CXCR2 is blocked to inhibit their chemotaxis, tumor angiogenesis can be reduced." (PMID 40597731, 2025). "The CXCR2 antagonist SX-682 synergized with immune checkpoint inhibitors by inhibiting the tumor infiltration of G-MDSCs, thereby enhancing anti-tumor immunity." (PMID 41254689, 2025). "Tumor-derived 22-HC recruits Tumor-derived 22-HC recruits TANs through CXCR2 signaling, promoting angiogenesis, immunosuppression, and tumor growth." (PMID 40607438, 2025). "CXCL5 binds the chemokine receptor CXCR2 and facilitates tumor proliferation, invasion, and angiogenesis via various signaling pathways in different types of cancer." (PMID 40050422, 2025). "Our findings suggest that Anwulignan mitigates BCP through a distinct synergistic mechanism, which involves the upregulation of PPARα expression to inhibit the expression of CXCR2, a reduction in tumor burden, and the promotion of osteoblast synthesis." (PMID 40079428, 2025). "Yang’s research highlights IL-8’s role in TANs recruitment and JAG2 expression, and the blockade of CXCR2 signaling reduces tumor growth and TANs numbers while enhancing CD8+ T cell activity." (PMID 40160822, 2025). "In murine cancer experiments, high expression of PAD4 activity and CXCR2 is observed in neutrophils of tumor growths and in the peripheral blood of lung and colon cancer patients." (PMID 40801583, 2025). "Flow cytometry further revealed an overall increase in the population of TAMs in tumours from mice treated with CXCR2 inhibitors." (PMID 41163221, 2025).
tumor (continued). "In NEPC cell models expressing IL-8/CXCR2, macrophage migration and tumour cell phagocytosis were markedly decreased." (PMID 41163221, 2025). "CD36 displayed strong positive correlations with immune receptors such as CCR1, CCR2, CCR4, CXCR1, and CXCR2, indicating its potential role in amplifying chemokine-receptor interactions and shaping immune cell trafficking within the tumor microenvironment." (PMID 41550652, 2025). "Studies have reported that the mRNA expression of CXCL8, a ligand for CXCR2, is markedly higher in tumor tissues, which is expected to be a candidate biomarker for ESCC." (PMID 40722739, 2025). "Consistently, tumour tissues from C4-2B/MDVR model mice presented increased lipid metabolism and AC-CoA activity relative to tumour tissues from C4-2B/NC model mice, both of which were suppressed upon CXCR2 inhibition." (PMID 41163221, 2025). "Current therapeutic strategies focus on the use of selective inhibitors such as JBI-589 and GSK484 to inhibit tumor progression by reducing CXCR2 expression and blocking neutrophil chemotaxis." (PMID 41465483, 2025). "Immunohistochemistry staining further confirmed the high expression of maresin-1 and 15d-PGJ2 in tumours from RM-1/CXCR2-bearing mice, with downregulation observed following CXCL15 mutation." (PMID 41163221, 2025). "Their involvement in tumor inflammation is primarily driven by key pathways such as the CXCL8/CXCR2 axis, NF-κB signaling, ROS production, and the formation of NETs." (PMID 40550048, 2025). "A number of ligands, including CXCL1, CXCL2, CXCL5, and CXCL8, converge on CXCR2, thereby coordinating neutrophil recruitment, angiogenesis, epithelial–mesenchymal transition, and tumor proliferation." (PMID 40943634, 2025). "In contrast to what was observed for the ligand CXCL8, a reduction of the levels of its receptor CXCR2, was observed in both normal and tumor thyroid cells following treatment with AZD5069 [1 μM]." (PMID 38900374, 2025). "Understanding the intricate roles of CXCR2 in both tumor immune evasion and metastasis offers promising avenues for developing more effective cancer treatments." (PMID 40124384, 2025). "In cancer studies, CXCR2 activation has been shown to promote the activation of tumor proliferation pathways." (PMID 40839237, 2025). "CXCR1 and CXCR2 inhibitors, including reparixin, have been evaluated in early clinical trials with the intent of disrupting IL-8-driven tumor biology." (PMID 41007766, 2025). "The CXCL8/CXCR2 axis emerges as a master regulator of tumor neovascularization, activating ERK1/2 and PI3K pathways in human intestinal microvascular endothelial cells (HIMECs) to drive proliferation, migration, and tubulogenesis." (PMID 40552145, 2025). "Selective inhibitors such as JBI-589 and GSK484 are currently being developed to inhibit tumor progression by reducing CXCR2 expression and blocking neutrophil chemotaxis." (PMID 41465483, 2025). "For example, in pancreatic adenocarcinoma, NF-κB-driven expression of CXCL5 fosters tumor progression via recruitment of CXCR2+ myeloid-derived suppressor cells (MDSC) and tumor-associated neutrophils." (PMID 41516196, 2025). "Compared with control tumours, tumours with activated IL-8/CXCR2 signalling were significantly larger." (PMID 41163221, 2025). "Primarily known for regulating neutrophil migration and recruitment to sites of inflammation, CXCR2 also influences the migration of immune-suppressive myeloid-derived suppressor cells (MDSCs) into the tumor microenvironment and the pre-metastatic niche." (PMID 40124384, 2025). "The results demonstrated that IL-8, in combination with its receptor CXCR2, impaired tumour responsiveness to PBMC treatment." (PMID 41163221, 2025). "Blocking CXCR2 significantly increased the response to chemotherapy and reduced tumor growth, angiogenesis, and metastasis." (PMID 40490643, 2025).
tumor (continued). "Meanwhile, CXCR2- CXCL2, along with CCR5-CCL5 obviously up-regulated in tumor-adjacent tissue, and they are linked with better OS, except for CXCL10." (PMID 40087771, 2025). "The results showed that CXCL7 overexpression enhanced tumor resistance to chemotherapy, whereas the addition of the CXCR2 inhibitor reversed this effect." (PMID 40368902, 2025). "Pembrolizumab is an anti-PD-1 antibody, and the treatment aimed to simultaneously block CXCR1/CXCR2 signaling and a key immune checkpoint involved in tumor immune evasion." (PMID 40427171, 2025). "Their trafficking and infiltration into solid tumors is frequently suboptimal, although this can be improved by engineering expression of chemokine receptors such as CXCR4, CXCR1, or CXCR2 to match tumor-secreted ligands." (PMID 40941014, 2025). "The consistent suppression of CAF markers and tumor volume upon CXCR2 knockdown in both settings highlights a mechanistically conserved role for this signaling pathway across cellular and organismal levels." (PMID 40490643, 2025). "Cancer-associated adipocytes secrete the chemokines CCL2/5 and IL-6/TNF-α, which promote tumour proliferation and immune escape by binding to CXCR2 and IL-6R/TNF-R on the surface of tumour cells." (PMID 40414892, 2025). "Research has shown that chemokine receptor agonists CXCR1 and CXCR2, produced by tumor cells, induce the formation of NETs, which act as a shield protecting tumor cells against cytotoxicity mediated by natural killer (NK) cells and T cells." (PMID 40801632, 2025). "Metabolic mass spectrometry (MS) analysis revealed significant upregulation of lipid metabolism in tumour-bearing mouse models generated from various tumour cell lines with an activated IL-8/CXCR2 pathway." (PMID 41163221, 2025). "Given the central role of macrophages in the TME and their impact on tumour progression, the interplay between IL-8/CXCR2 signalling, CD47 regulation, and macrophage infiltration holds significant clinical relevance." (PMID 41163221, 2025). "SB225002, a selective inhibitor of CXCR2, significantly reduces infiltration of neutrophils and enhances anti-tumor T cell activity, promoting the therapeutic effect of cisplatin." (PMID 40050933, 2025). "CXCR2 plays a role in inhibiting cell proliferation in normal cells; however, in the tumor microenvironment, its presence paradoxically leads to increased tumor cell proliferation." (PMID 40647424, 2025). "Next, to investigate the mechanisms of GB4-BPL@siCXCR2/pPTEN, the mRNA expression levels of PTEN and CXCR2 in tumor tissues were detected by RT‒qPCR." (PMID 40860155, 2025). "Emerging studies have shown that CXCR2 blockade can synergize with ICIs to overcome resistance in immunosuppressive tumours." (PMID 41163221, 2025). "A study using a mouse model of carcinogenesis showed that proinflammatory IL-17-mediated CXCR2 axis activation results in a high population of neutrophils at the tumor site." (PMID 40727443, 2025). "The activation of the CXCL8/CXCR2 signaling pathway is believed to suppress anti-tumor immunity, promote tumor cell invasiveness, and facilitate immune evasion." (PMID 40573881, 2025). "Tumor-associated neutrophils (TANs) are pivotal immune cells that populate the tumor microenvironment (TME) and can be drawn in by IL-8 through CXCR1/CXCR2 signaling." (PMID 40281554, 2025). "Dysregulation of these writers reshapes the tumor microenvironment (TME): for example, METTL3 overexpression in tumor cells promotes myeloid-derived suppressor cell (MDSC) accumulation via the BHLHE41–CXCL1/CXCR2 axis, dampening CD8+ T-cell responses." (PMID 41280938, 2025). "C-X-C chemokine receptor 2 (CXCR2), particularly the C-X-C motif chemokine ligand 5 (CXCL5)/CXCR2 axis, is also crucial in tumor lymphatic metastasis and chemoresistance." (PMID 40564091, 2025).
tumor (continued). "In vivo, co-injection of SCC25 cells with GFs significantly promoted tumor growth and stromal CAF marker expression, whereas CXCR2 knockdown in GFs led to a ~ 40% reduction in tumor volume and reduced αSMA/vimentin-positive CAFs." (PMID 40490643, 2025). "A substantial body of research substantiates that CC chemokines (e.g., CCL2, CCL5) and CXC chemokines (e.g., CXCL1, CXCL2, CXCL5) recruit diverse immune cells, such as CCR2+ monocytes and CXCR2+ neutrophils, to tumor sites." (PMID 39206194, 2024). "Further, we found that myeloid cells positive for both CCR1 and CXCR2 were accumulated around the tip of the tumor in human clinical CRC specimens." (PMID 38750114, 2024). "The suppression of anti-tumor immunity by METTL3 through the m6A–BHLHE41–CXCL1/CXCR2 axis contributes to tumor immune evasion and progression." (PMID 39759516, 2024). "This study unveils how NKX2‐1 modulates the infiltration of tumor‐promoting neutrophils by inhibiting CXCLs/CXCR2‐dependent mechanisms." (PMID 39113226, 2024). "The inhibition of CXCR2 chemokine receptor with specific inhibitor SB225002 decreased the infiltration of tumor‐promoting neutrophils, resulting in reduced tumor growth in NKX2‐1‐low tumors." (PMID 39113226, 2024). "The interplay between UPP1high tumor cells and SPP1+ macrophages was linked with a variety of chemokines, including CCL2_CCR2, CCL3_CCR5, CXCL3_CXCR2, and CXCL8_CXCR1, as well as interactions such as IL1B_IL1_receptor and TGFB1_TGFbeta_receptor1." (PMID 38331898, 2024). "Blockade of the CXCL5/CXCR2 signaling axis can increase the sensitivity of immunotherapy and delay tumor progression." (PMID 39034411, 2024). "CXCR2 (CXC chemokine receptor 2) is inhibited by blocking the recruitment of pro-tumour neutrophils to the TME, which blocks activation signals such as G-CSF or TNFα and ROS production by inhibiting contact with T cells." (PMID 39720730, 2024). "It is important to account for tumor stage when considering the tumor-suppressive effect of targeting CXCR2." (PMID 38358352, 2024). "By adding a CXCR2 antagonist AZD-5069 in both scenarios, the NTI-chip also enabled us to tease out blockade of soluble factors and blockade of direct cell–cell contact as two different tumor-suppressive mechanisms of CXCR2 inhibition." (PMID 38898176, 2024). "In KRAS-mutant CRC mouse models, both pharmacological and genetic inhibition of CXCR2 counteracts this immunosuppression and hinders tumor progression." (PMID 39795864, 2024). "It affects tumor migration and proliferation by binding to a particular receptor called CXCR2, which initiates a series of various signaling events." (PMID 39860963, 2024). "This engineering design helped reveal the important role of direct contact in the tumor-promoting mechanisms of neutrophils and the tumor-suppressive mechanisms of CXCR2 inhibition." (PMID 38898176, 2024). "The combination of CXCR2 inhibitors with anti-PD1 (programmed cell death 1) treatments shows potential in transforming pro-tumour TANs into anti-tumour counterparts." (PMID 39320855, 2024). "Using snRNA-seq and imaging mass cytometry, CD8+ T cells were spatially excluded from the contiguous PanCK+ CXCL1+ tumor cell and tumor-infiltrated neutrophil (CXCR2+ CD11b+ CD15+) communities." (PMID 38786066, 2024). "YTHDF1 impairs anti‐tumour immunity via an m6A‐p65‐CXCL1/CXCR2 axis and serves as a therapeutic target for ICB in colorectal cancer." (PMID 39568154, 2024). "Focusing on PCa, therapeutic inhibition of IL-8 or its receptors CXCR1 and CXCR2 demonstrated reduced tumour growth and increased treatment sensitivity in resistant tumours." (PMID 39199570, 2024). "CXCR2+ MDSCs were recruited to CXCL2- and MIF-expressing human bladder tumors and those tumor-associated MDSCs exhibited stronger suppression of T cells than the counterpart cells from the peripheral blood of cancer patients or healthy donors." (PMID 38786066, 2024).